TRIM28 (tripartite motif containing 28)
Diseases named in the same sentence as TRIM28 in open-access papers (continued):
Sharing a sentence is not in itself a finding about the gene and the disease.
tumor (continued). "Therefore, our study establishes XAF1 as an intrinsic antagonist of TRIM28, illuminating a novel mechanism underlying its tumor suppression function." (PMID 39532800, 2024). "Next, we asked whether XAF1 tumor suppression function is linked to the TRIM28-destabilizing activity." (PMID 39532800, 2024). "Investigating whether TRIM28 is implicated in these two forms of cell death is essential for a comprehensive understanding of its role in tumor biology." (PMID 39534556, 2024). "However, the expression of TRIM28 was positively associated only with tumor purity (p < 0.001) in PRAD and was also related to tumor immune infiltration in PRAD, ESCA, and PAAD." (PMID 37781084, 2023). "The enrichment of TRIM28 expression was associated with GSCs, homing to the core of the tumor." (PMID 36139694, 2022). "Its down-regulation mechanism may be related to DNA hypermethylation of gene promoter or loss of the copy number of the gene, histone deacetylation caused by deregulation of HDACs or degradation of FBP1 in tumor cells caused by the E3 ligase TRIM28." (PMID 36237339, 2022). "So, we hypothesize that TRIM28 is linked to immune cell infiltration and significantly promotes tumor progression in LIHC." (PMID 36238495, 2022). "Because of their role as potential risk factors for poor prognosis, TRIM28 expression, age, tumor size, vascular or nerve invasion condition, lymph node condition, histologic grade, TNM stage, ER, PR, HER-2, Ki67 expression, and molecular subtype were selected as risk variables." (PMID 33817325, 2021). "Furthermore, we observed a significant enrichment of TRIM28-associated transcription profiles with stem cell markers in 26 out of 27 tested tumor types." (PMID 33810347, 2021). "Here, we present that TRIM28 is closely associated with tumor de-differentiation in TCGA solid tumors, and for several tumor types, TRIM28 possesses potential diagnostic value in predicting the stemness high phenotype (which corresponds to worse patient survival)." (PMID 33810347, 2021). "We used the TISIDB and Tumor IMmune Estimation Resource (TIMER) databases to assess whether TRIM28 expression was associated with the level of immune infiltration across human tumors." (PMID 33091876, 2020). "Since it has been reported that TRIM28 interacts with AMER1 (WTX) we postulated that tumours with mutations in AMER1 might share common features with TRIM28–mutated tumours." (PMID 29912901, 2018). "All TRIM28-mutant tumours showed the rare monomorphic epithelial histology, suggesting that loss of TRIM28 expression could be a useful marker to define a group of tumours with excellent prognosis." (PMID 29912901, 2018). "The modulation of signaling pathways found in this study may be attributed the pleiotropic properties of TRIM28, specifically impacting tumor-associated stromal compartments." (PMID 29631612, 2018). "Immunohistochemistry for TRIM28 protein was done for tumours 37T, 39T and W117 to determine whether mutations in TRIM28 led to loss of protein expression." (PMID 29912901, 2018). "We hypothesise that loss of TRIM28 expression or the presence of TRIM28 mutation, in combination with monomorphic epithelial histology, can be used to identify the good prognosis S1 subtype of tumours." (PMID 29912901, 2018). "We, therefore, sought other tumours to determine whether loss of function of TRIM28 was a shared feature of monomorphic epithelial tumours." (PMID 29912901, 2018). "By dissecting TRIM28-associated pathways in stromal fibroblasts and epithelial tumor cells, we performed comprehensive proteomic analyses of molecular networks within the tumor microenvironment." (PMID 29631612, 2018). "Among these 18 pairs, a heterozygous frameshift mutation in exon 13 of TRIM28 (c.1935delinsGA) was detected in a sporadic tumour (W117), though a second inactivating mutation or deletion could not be detected from the exome data." (PMID 29912901, 2018).
tumor (continued). "We assessed whether inhibition of the epithelial-to-mesenchymal (EMT) transition, which results in the loss of pluripotency, might explain the decrease in tumor growth upon TRIM28 knockdown." (PMID 27845900, 2017). "Moreover, it was shown that TRIM28 expression was increased with tumor stage and TRIM28 expression was positively associated with tumor stage." (PMID 28394358, 2017). "Moreover, the RNA-Seq results and IHC staining validated our finding that TRIM28 downregulation led to the loss of tumor cells' pluripotency." (PMID 27845900, 2017). "TRIM28 protein expression positively correlates with tumor aggressiveness, which may indicate TRIM28 association with a stem-like phenotype." (PMID 27845900, 2017). "Overall, the absence of additional driver variants in tumours arising on a background of WT1 or TRIM28 predisposition was significant, even when solely considering high risk variants, whether compared to other predispositions or to control tumours (p<0.05, Fisher’s exact test)." (PMID 39665570, 2025). "Therefore, further investigations are needed to determine whether TRIM28 expression could affect the spatial distribution of tumor-associated immune cells." (PMID 37865804, 2023). "If this parent-of-origin effect is supported, DNA methylation analyses at the PEG3 imprinting control region and loss of heterozygosity and PEG3 expression analyses in tumours from individuals with TRIM28 mutations might help to provide a mechanistic explanation." (PMID 30885698, 2019). "Therefore, we hypothesized that the inhibition of tumor growth in TRIM28-downregulated MDA-MB-231 cells is associated with the reduction of the CSC population." (PMID 27845900, 2017). "We recently developed a unique in vivo genetic mouse tumor model where deletion of Trim28 in prostate epithelial cells results in tumors with decreased cellular plasticity and increased apoptosis." (PMID 41508128, 2026). "At 1 month after tumor induction, we observed elevated dsRNA staining in both NPp53 and Trim28 deleted NPp53T tumors." (PMID 41508128, 2026). "Using Picrosirius Red staining, we visualized collagen fibers 1 month after tumor induction, which confirmed the increase in interstitial collagen fibers in Trim28 deleted NPp53T compared to NPp53 prostates." (PMID 41508128, 2026). "WGS data were available for 31 cases (46 tumor, 41 control samples), and targeted Sanger sequencing was performed on 30 WT samples (22 stromal-type, 8 epithelial-type) suspected of WT1 or TRIM28 mutations." (PMID 40340749, 2025). "This discovery not only elucidates the synergistic mechanism of MAGE-A4 and TRIM28 in tumor development but also provides a theoretical foundation for developing novel anti-cancer strategies targeting this pathway." (PMID 39905312, 2025). "Our bioinformatics analysis revealed that the expression levels of DDX21 and TRIM28 in tumor tissues were elevated compared with normal tissues, and they were classified as high‐risk prognostic factors." (PMID 41194971, 2025). "To validate the seemingly preordained driver landscape of tumours in WT1 and TRIM28 predisposition, we searched for additional cases amongst children with bilateral tumours and/or a family history of Wilms." (PMID 39665570, 2025). "Our study also provides evidence that TRIM28 elevation due to XAF1 inactivation protects tumor cells from apoptotic stresses." (PMID 39532800, 2024). "TRIM28 can additionally facilitate tumor cell proliferation as it is directly targeted by microRNAs." (PMID 39534556, 2024). "Further, TRIM28 protein showed higher levels in GBM as measured by quantitative proteomics data from the Clinical Proteomic Tumor Analysis Consortium (CPTAC) and immunohistochemistry from the Protein atlas." (PMID 39302097, 2024). "It is worth noting that TRIM28 is also active during developmental stages, exhibiting notably high expression levels in ESCs as well as various tumor types, a topic that will be explored in greater detail." (PMID 39534556, 2024).
tumor (continued). "(E) The mmunohistochemistry assay was performed to show the TRIM28 protein expression in the tumor tissue section derived from U87-Luc/siNT and U87-Luc/siPITAR#1 tumors." (PMID 39302097, 2024). "In the present study, we found that XAF1 destabilizes TRIM28 to suppress tumor cell malignancy whereas TRIM28 destabilizes XAF1 to protect tumor cells from apoptotic stresses." (PMID 39532800, 2024). "Hence, inhibiting TRIM28 may render tumor cells more susceptible to chemotherapy." (PMID 39534556, 2024). "TRIM28 was highly enriched in the core of the tumor and correlated with the expression of stem cell‐related genes." (PMID 39534556, 2024). "TRIM28 appears to play a crucial role in regulating tumor cell apoptosis, necroptosis, and autophagy." (PMID 39534556, 2024). "Ectopic expression of TRIM28 promoted tumor growth, elevated PD‐L1 expression, and inhibited T cell activation." (PMID 39534556, 2024). "Together, these support that XAF1 suppresses tumor cell malignancy at least in part by targeting TRIM28." (PMID 39532800, 2024). "Simultaneously, ectopic TRIM28 expression promotes tumor growth in mice and inhibits T-cell activation." (PMID 39100077, 2024). "By recruiting TRIM28 to another E3 ligase ZNF313, XAF1 promotes ubiquitination and proteasomal degradation of TRIM28, thereby antagonizing its tumor-promoting activity." (PMID 39532800, 2024). "TUNEL and cl-PARP immunoblot assays of tumor tissues showed that apoptosis-inducing effect of XAF1 is substantially lower in TRIM28−/− tumors compared to TRIM28+/+ tumors, supporting the TRIM28-dependency of its growth inhibition function." (PMID 39532800, 2024). "In NSCLC cells, TRIM28 deficiency blocks transforming growth factor beta (TGF-β)-induced EMT, reducing tumor cell migration and invasion by regulating histone acetylation and methylation on E-cadherin and N-cadherin promoter regions." (PMID 39160596, 2024). "These roles collectively emphasize the complexity of TRIM28’s impact on tumor biology and its potential as a target for therapeutic interventions." (PMID 39534556, 2024). "We found that as comparing with adjacent normal tissues, TRIM28 protein expression was stronger in most tumor tissues, which was consistent with the data from TCGA and GTEx databases." (PMID 37781084, 2023). "Since tumor mutational burden (TMB) can be used to predict the tumor immune signature, we performed correlation analysis between TRIM28 expression and TMB." (PMID 37357254, 2023). "We further found that high expression of lnc-TRIM28-14 was positively correlated with poor tumor differentiation, peritoneal metastasis, and increased TNM stage." (PMID 36690975, 2023). "Ectopic TRIM28 expression facilitated tumor growth, increased PD-L1 expression, and suppressed T cell activation in mice." (PMID 37357254, 2023). "Administration of the PD-L1 or TBK1 inhibitor significantly alleviated the TRIM28-induced tumor progression." (PMID 37357254, 2023). "To further detect and verify the actual protein expression of TRIM28 in tissues, we tested multiple tumor tissues using tissue microarray." (PMID 37781084, 2023). "Based on these results, we strongly believe that TRIM28 regulates the tumor microenvironment composition and immune response, thereby affecting the response to antitumor immunotherapy." (PMID 37781084, 2023). "Further exploration is warranted to assess the broader impact of TRIM28 on the NF-κB-dependent expression of cytokines and chemokines within the immunosuppressive tumor microenvironment of NSCLC." (PMID 37865804, 2023). "In conclusion, TRIM28 helps maintain the virus in a latent state and suppresses the generation of anti-tumor immune environment." (PMID 36756159, 2023).
tumor (continued). "When analyzing the tumor microenvironment of TRIM28-expressing NSCLC tumors, we observed an increase in CD14+ cells." (PMID 37865804, 2023). "To further investigate the association between TRIM28 expression and MDSC infiltration, we examined the percentages and numbers of MDSCs infiltrating the tumor-burdened lungs in KP-TRIM28 and KP mice." (PMID 37865804, 2023). "We observed that mice bearing tumors derived from cells with ectopic TRIM28 expression exhibited faster tumor progression than the control group." (PMID 37357254, 2023). "We further quantified the IHC data and showed that TRIM28 expression were higher in tumor tissues than that in adjacent normal tissues in BLCA, BRCA, CESC, COAD, LUAD, GBMLGG, PRAD, and UCEC." (PMID 37781084, 2023). "Using the integrated bioinformatics analyses, mouse models, and clinical observations, we tried to uncover the effect of TRIM28-mediated PD-L1 upregulation on tumor growth and anti-tumor immunity." (PMID 37357254, 2023). "Analysis of TRIM28 expression levels in conjunction with clinicopathological features revealed that high TRIM28 expression correlated with larger tumor size, lymph node metastasis, distant metastasis, and advanced pathological stage." (PMID 37865804, 2023). "We found that TRIM28 expression enhanced immune cell infiltration, especially in BRCA, GBM, LIHC, and PRAD, and that TRIM28 expression levels were positively related to tumor purity (p < 0.001) and the presence of CD4+ T cells (p < 0.001) in BRCA." (PMID 37781084, 2023). "We found that inhibiting TRIM28 in syngeneic mouse models reduced MDSCs in the tumor microenvironment and rendered the tumors more responsive to PD-1 blockade." (PMID 37865804, 2023). "Furtherly, to explore the association of TRIM28 and PD-L1 in G.C., we extracted the data of G.C. patients from the Cancer Genome Atlas (TCGA) and ACRG databases and evaluated the expression of TRIM28 and PD-L1 in the tumor and adjacent normal tissues." (PMID 37357254, 2023). "Herein, we demonstrated that TRIM28 is pivotal in promoting the chemokine-driven recruitment of MDSCs through the NF-kB signaling pathway within the tumor microenvironment." (PMID 37865804, 2023). "Structure-function evaluations have demonstrated that TRIM28’s tumor-promoting functions rely on its E3 ubiquitin ligase activity." (PMID 37865804, 2023). "The reduction of TRIM28 gene expression reduced the self-renewal ability of BCSCs and resulted in a significant decrease in tumor growth." (PMID 36756159, 2023). "As expected, depletion of TRIM28 led to a profound reduction in MDSCs, whereas overexpression of TRIM28 increased MDSC infiltration in the tumor microenvironment." (PMID 37865804, 2023). "Our findings prompted us to explore the role of TRIM28 in tumor progression and its impact on the tumor microenvironment." (PMID 37865804, 2023). "To explore the potential impact of TRIM28 on tumorigenesis in vivo, we employed a syngeneic G.C. mouse model to validate the importance of TRIM28 in regulating the tumor immune response." (PMID 37357254, 2023). "Herein, we observed that TBK1 and mTOR inhibitors strongly prevented the TRIM28-induced upregulation of PD-L1 expression and inhibited tumor growth in vivo." (PMID 37357254, 2023). "Meanwhile, a strong staining intensity of TRIM28 protein expression was mainly found in both normal and tumor tissues of KIRC, LIHC, STAD, and ESCA." (PMID 37781084, 2023). "In mice infected with lenti-TRIM28-Cre (KP-TRIM28), histological analysis revealed significantly larger tumor sizes and areas in the lungs compared to control KP mice." (PMID 37865804, 2023). "Results showed that suppressing PD-L1 expression inhibited the TRIM28-induced tumor growth in the syngeneic mouse model by increasing the CD8+ T cell infiltration." (PMID 37357254, 2023).
tumor (continued). "Consistent with the findings in cultured cells, the length of de novo L1 inserts in tumor samples collected from patients with high levels of TRIM28 expression is significantly shorter than in patients with low TRIM28 expression." (PMID 37070200, 2023). "In summary, TRIM28 exhibits high expression in NSCLC tumor tissues and positively correlates with MDSC infiltration in the tumor microenvironment, potentially contributing to enhance tumor progression." (PMID 37865804, 2023). "Consistently, the combination of TRIM28 inhibition with anti-PD-1 resulted in sustained control of tumor progression." (PMID 37865804, 2023). "Co-administration of CDK4/6 inhibitor palbociclib obviously enhanced the therapeutic efficacy of SETDB1 depletion on tumor growth by protecting TRIM28-mediated p-RB from proteasomal degradation both in vitro and in vivo." (PMID 38057834, 2023). "High expression levels of TRIM28, H2AX or CDK4 were significantly associated with tumor recurrence in an independent cohort of HCC." (PMID 37870748, 2023). "We also evaluated the correlation of TRIM28 expression with various parameters of immune infiltration using Tumor Immune Estimation Resource (TIMER) database." (PMID 37870748, 2023). "Our findings underscore the potential of pharmacologic inhibition of TRIM28 as a promising strategy to counter tumor-induced immune tolerance and enhance the effectiveness of PD-1 blockade." (PMID 37865804, 2023). "Both TRIM28 knockout and anti-PD-1 treatment alone reduced tumor size and weight compared to the control." (PMID 37865804, 2023). "In summary, these results suggest that TRIM28 in tumor cells induces the activation of the NF-κB pathway, which contributes to the expression of CXCL1." (PMID 37865804, 2023). "Initially, we overexpressed TRIM28 in the KP adenocarcinoma model to investigate its impact on tumor development and MDSC levels." (PMID 37865804, 2023). "The tumor suppressive function exerted by TRIM28 is closely tied to its control over the expression of pro-tumorigenic chemokines." (PMID 37865804, 2023). "It has been shown that TRIM28 not only associates with MAGE-C2 but also enhances the E3 ligase activity of MDM2, which implied that TRIM28 is possibly involved in blocking the tumor suppression of MGAE-C2." (PMID 35927984, 2022). "TRIM28, which is a transcription factor involved in gene regulation, is also involved in the proliferation of tumor cells." (PMID 35053605, 2022). "Our study also sought to determine if there was a difference in tumor immune microenvironment between LIHC patients with low TRIM28 levels and patients with high TRIM28 levels." (PMID 36238495, 2022). "Some of the RNAs that encode the proteins regulating the cell cycle were increased (such as p21) or decreased (such as cyclin D2) in TRIM28 KO cell clones; a tumor marker, the MAGE (melanoma antigen) family, which is involved in cell proliferation was reduced." (PMID 35743282, 2022). "TRIM28 thus seems to represent a target for GB invasion, being enriched in the tumour core with MES subtype–related and stem cell genes." (PMID 34500575, 2021). "TRIM28 expression is higher in tumor tissue when compared to adjacent healthy tissue in many distinct tumor types." (PMID 33810347, 2021). "A recent study has confirmed that TRIM28 is a positive regulator of cell proliferation and tumor growth." (PMID 33817325, 2021). "The mean expression of TRIM28 correlates significantly with the mean stemness index (mRNA-SI) across TCGA solid tumor types, suggesting that the more de-differentiated a tumor is, the higher the expression of TRIM28." (PMID 33810347, 2021). "We further analyzed the level of TIF1 family members in relation to the tumor grade using transcriptomic data and observed significantly higher TRIM28 expression in de-differentiated tumors, while the level of other TIF1 members was relatively unchanged." (PMID 33810347, 2021).